FGF2 (fibroblast growth factor 2)
Diseases named in the same sentence as FGF2 in open-access papers (continued):
Sharing a sentence is not in itself a finding about the gene and the disease.
tumor (continued). "This cross-talk occurs when the tumor cells secrete TGF-β1, which promotes VSV infection in CAFs, and CAFs secrete FGF2, which reduces innate anti-viral retinoic acid-inducible gene I (RIG-I) expression in pancreatic tumor cells." (PMID 33167307, 2020). "Of the cultured tumour cells, only MC38 expressed detectable Fgf2 RNA and this was several hundred folds less than the amounts from TAMs." (PMID 32792542, 2020). "In this study, we demonstrate that fibroblast growth factor 2 (FGF2) plays a pivotal role in shifting TAMs towards a pro-tumourigenic, M2-like phenotype in the tumour microenvironment." (PMID 32792542, 2020). "Cell culture supernatants of the Mock and FGFR2-Fc–expressing tumor cells were collected to assess the specific binding of FGFR2-Fc to FGF1 and FGF2." (PMID 32076044, 2020). "Within the tumor, MCs release angiogenic compounds including IL-8, VEGF, FGF-2, NGF, heparin, tryptase, chymase, and TGF-β." (PMID 31256327, 2020). "CAFs have been found to facilitate tumor angiogenesis by secreting a variety of angiogenic factors, such as vascular endothelial growth factor (VEGF) and FGF2." (PMID 33213510, 2020). "Another growth factor, FGF2, secreted by HCC and expressed preferentially in tumour tissue compared to CLD, induces T-cadherin on LSEC." (PMID 32982772, 2020). "FGF-2, also known as basic FGF (bFGF), is the most characterized pro-angiogenic mediator in physiological conditions as well as during tumor progression." (PMID 31690961, 2020). "FGF-2 and its receptor FGFR1 can enhance tumor cell proliferation and migration by acting on stromal cells and cancer cells." (PMID 33213510, 2020). "These embryonic bridging macrophages secrete numerous genes shared by the perivascular macrophages that drive tumor angiogenesis including the angiopoietin receptor, Tek, the VEGF co-receptor Nrp1, growth factors (Fgf2, Pgf) and MMPs (Mmp2, Mmp9)." (PMID 32484158, 2020). "For pericyte coverage, FGF-2 amplifies the PDGF-B-PDGFRβ signaling at both ligand and receptor levels to ensure appropriate remodeling and maturation of tumor vessels 19,24." (PMID 32709869, 2020). "Mast cell- and macrophage-derived growth factors that can promote tumor development and angiogenesis include TNF-α, TGF-β1, FGF-2, VEGF, platelet-derived growth factor (PDGF), IL-8, osteopontin, and nerve growth factor (NGF)." (PMID 32508920, 2020). "For example, TAMs secrete TGF-β, vascular endothelial growth factor (VEGF), fibroblast growth factor 2 (FGF2), FGF10, fibroblast growth factor receptor 2 (FGFR2), and several MMPs to support tumor growth and immune protection." (PMID 33224886, 2020). "Fibrinogen can promote the adhesion, proliferation, and migration of tumour cells by binding with vascular endothelial growth factor (VEGF) and fibroblast growth factor-2 (FGF-2)." (PMID 31781312, 2019). "With the baseline secretion rates, the model predicts that the pro-angiogenic factors (VEGF and FGF2) and anti-angiogenic factors (TSP1 and PF4) have significantly different distribution patterns in tumor tissue." (PMID 31379588, 2019). "BET inhibitors also induce adaptive responses by upregulating FGF2 production by HSCs and FGFR expression in UM tumor cells." (PMID 30610113, 2019). "Analysis of fibroblasts derived from biopsies of these lesions revealed that fibroblast growth factor-2 (FGF-2) is synthesized at all three stages and by normal dermal fibroblasts, FGF-2 expression being correlated to angiogenesis and tumor progression." (PMID 31533326, 2019). "As an example, the presence of TNF, IL-1, IFN-γ and hypoxic conditions in the TME induces the secretion of proangiogenic and immune suppressive factors (including EGF, PDGF, fibroblast growth factor 2, FGF-2, VEGF, IL-6 and IL-10) allowing tumor proliferation." (PMID 30781344, 2019).
tumor (continued). "The majority of each pro-angiogenic factor in the tumor (∼81% of VEGF and ∼50% of FGF2) is bound to the cell surface, while only a small percentage of the anti-angiogenic factors (∼16% of PF4 and ∼12% of TSP1) exists on the cell surface." (PMID 31379588, 2019). "The bFGF or FGF-2, another multiple function factor, can enhance the proliferation, migration, and survival of endothelial cells as well as tumor angiogenesis." (PMID 31652997, 2019). "FGF2 has been reported to play an important role in tumor metastasis; thus, we next wanted to evaluate the role of PSS in inhibiting tumor cell invasion and metastasis." (PMID 31035725, 2019). "Our work suggests that disrupting the supportive role that ASCs provide for tumor cells, either by preventing ASC migration to the chemo-residual tumor microenvironment or by inhibiting the signaling associated with ASC release of growth factors such as FGF2, may prevent TNBC recurrence." (PMID 30594967, 2019). "Recent data suggest B19 interferes with downstream FGF2 signaling via alterations to MAPK, triggering cell cycle arrest and halting tumor cell proliferation." (PMID 30594967, 2019). "In this pro-tumor state, myeloid cells represent a crucial source of angiogenic factors producing VEGF, fibroblast growth factor 2 (FGF2), CXCL8 (CXC-chemokine ligand 8), WNT7B, and BV8." (PMID 31572387, 2019). "In a tumor with medium HSPG expression, the concentration of FGF2-bound dimers shows the largest decrease (6.5-fold)." (PMID 31379588, 2019). "Notable downregulation of growth factors (VEGFD, FGF2, PGF, TNF-α) and cytokine IL-1A was observed in tumor cells upon treatment with 5a." (PMID 31842391, 2019). "In hypoxia state, tumor cells secrete platelet derived growth factor (PDGF), transforming growth factor- β (TGF- β), and fibroblast growth factor-2 (FGF-2)." (PMID 31741805, 2019). "Previous studies indicate that TNBC cells are dependent on fibroblast growth factor 2 (FGF2) for their growth and survival, which has led to the clinical use of FGFR tyrosine kinase inhibitors to slow primary tumor growth and progression." (PMID 30594967, 2019). "This percentage increased for FGFR1‐15R and FGFR1‐25Ra 30 min after FGF‐2‐treatment as compared with FGFR1‐WT confirming previous data on enhanced recycling capabilities of FGFR1‐15R and FGFR1‐25Ra in tumor cells." (PMID 30950230, 2019). "Transforming growth factor alpha (TGFα), FGF-2, and EGF were increased in the G59 PDX group compared to the G68 PDX group suggesting a more angiogenic tumor profile in the less cachectic G59 PDX group." (PMID 30513792, 2018). "These include FGF2 and FGF7 that promote tumor development, cancer cell proliferation, survival and wound healing responses, as well as TGFß2, which can promote cancer progression, cancer cell invasion and metastasis." (PMID 30325954, 2018). "Again, FGF-2 protein in Matrigel potently increased the NG2+ pericyte content and pericyte coverage in tumor vessels." (PMID 29423271, 2018). "Knowing that FGF-2 potently recruited pericytes onto tumor vessels, we next investigated the functional properties of FGF-2-modulated tumor vessels." (PMID 29423271, 2018). "PTX3 interacts with FGF2 and other FGF family members, thus acting as a multi-FGF antagonist able to inhibit FGF-dependent neovascularization and tumor growth." (PMID 30443492, 2018). "Previous studies have investigated the angiogenic expression profiles in HNSCC tumour tissues compared to normal tissue and have identified VEGF, IL-8/CXCL8, FGF-2 and HGF as key mediators of angiogenesis in HNSCC patients." (PMID 30001714, 2018). "Some of these factors and others can also stimulate tumor proliferation and survival (e.g. EGF, PDGF, TGF-β1, HGF and FGF-2)." (PMID 29728948, 2018). "The elevation of tumor invasion is supported by our sequencing results that demonstrated TNFα up-regulates invasion-related genes of MMP1, MMP9, MMP14, LAMB3, and FGF2 which all have been previously reported to increase OSCC cancer invasion." (PMID 30018735, 2018).
tumor (continued). "Recently, the characterization of the molecular bases of FGF2/PTX3 interaction has allowed the identification of NSC12, the first low molecular weight pan-FGF trap able to inhibit FGF-dependent tumor growth and neovascularization." (PMID 30349543, 2018). "The first set of four events involves three genes, FGF2, CCNE1, RNF43, whose tumor-specific APA regulations indicate clear length modulations of the 3’ UTR in cancer." (PMID 30005633, 2018). "Previous studies found that the expression of VASH1 was restricted to ECs of blood vessels in the tumor stroma, and correlated with the expression of VEGF and FGF-2 in tumor cells." (PMID 29535800, 2018). "In cancer, different tumor cell lines express different members of the FGF family, including FGF2, and/or display an aberrant activation of the FGF/FGFR system." (PMID 30443492, 2018). "Since NT4 binds HSPGs with sub-nanomolar affinity, we investigated the effects of the nude peptide, in terms of modulation of invasiveness and angiogenesis, on fibroblast growth factor 2 (FGF2) and thrombin-stimulated endothelial and tumor cells." (PMID 29566097, 2018). "To study the role of FGF-2 in modulating pericytes in tumor vessels, we selected two cell lines as FGF-2-negative and -positive tumors for in vivo mice tumor models." (PMID 29423271, 2018). "We conclude that the overexpression of FGF-2 and the overexpression or genetic alteration of FGFR-3 occur in minimally overlapping tumor sets." (PMID 28515962, 2017). "MiR-195 exerts its tumor suppressive function by targeting CCND1 and FGF2 and restraining the activity of the Wnt/β-catenin signaling." (PMID 28740507, 2017). "Consistently, neutralization of IGF-1 in TAB-tumor cell co-cultures led to inhibition of FGFR-3 induction and FGF-2 secretion by tumor cells." (PMID 28928360, 2017). "One such example involves the release of platelet-derived growth factor (PDGF) from the K14HPV16 cervical epithelium, which leads to expression of fibroblast growth factors 2 and 7 (FGF-2 and FGF-7) in the stroma to promote angiogenesis and tumor cell growth." (PMID 28792475, 2017). "As expected, expression levels of HIF-1αand AAFs, including VEGF, PDGF-B, FGF-2 and PlGF, were significantly reduced in PNR of metformin-treated 4T1 tumor tissue." (PMID 29088755, 2017). "FGF-2/FGFR-3 signaling is involved in angiogenesis, tumor progression, and therapy resistance in other cancers." (PMID 28928360, 2017). "MCs express pro-angiogenic factors as VEGF-A, FGF-2, PDGF, tryptase, chymase, and MMPs promoting tumor growth." (PMID 27462915, 2016). "Dual blocking of VEGF and FGF2 has been achieved with the use of a fusion protein containing peptides of both VEGFA and FGF2, this fusion protein was used to vaccinate tumour bearing mice." (PMID 26620208, 2016). "We co-stained tumor sections for phospho-FRS2 and murine CD31 to determine if FGF2 signaling was affected by [NSIS6S]-[NSIS]5 treatment in specific cell types in tumors." (PMID 27490176, 2016). "IL-1β, which is expressed in subsets of cells in the HL tumor microenvironment, activates PI3K signaling pathway to upregulate FGF2 production through NF-κB." (PMID 27007053, 2016). "Antibodies against human VEGF, IGF-1, FGF2, PDGF, TGF-β, IL-6, IL-8 and SDF-1 were individually added to primary human ECs conditional medium (phEC-CM) before treating tumor cells." (PMID 26762853, 2016). "On the other hand, a qPCR analysis using mouse-specific primers revealed that the expression of VEGFA, FGF2, FGFR2 and platelet-derived growth factor receptor A (PDGFRA) was upregulated in the bevacizumab-treated tumour stroma." (PMID 26635184, 2015). "FGF2 activates FGF receptors (FGFRs) on endothelial cells, resulting in increased tumor vascularization and dissemination of metastatic cells." (PMID 25609197, 2015). "Although many genes were downregulated in GB-1 3D culture relative to the parental tumor (e.g. FGFR3, TGFβ1 and TYMP), certain genes were now upregulated (e.g. FGF2, ANGPT1 and EFNA3)." (PMID 26203665, 2015).
tumor (continued). "Basic fibroblast growth factor (bFGF or FGF-2) and its receptor (FGFR-1, CD331) have been targeted in pre-clinical mouse models to evaluate their anti-angiogenic and anti-tumor effects." (PMID 26510973, 2015). "VEGF-A, FGF-2 and EGF, factors which characterize the angiogenic milieu, were able to significantly increase trypsinogen 4 expression by tumor-EC." (PMID 26318044, 2015). "Relatively high expression levels of FGF2, FGF7 and HGF are observed with fibroblasts established from tumor (HECAF2111) and three types of fibroblasts established from normal tissue (HFF75, HEF1173, and HEF2111)." (PMID 25884729, 2015). "The combination treatment of FGF2-neutralizing Ab and bevacizumab also reduced MVD in the tumour produced by Y-MESO-14 cells compared with the bevacizumab treatment in combination with control IgG." (PMID 26635184, 2015). "Trypsinogen 4 expression was upregulated by the combined action of VEGF-A, FGF-2 and EGF, angiogenic factors representative of the tumor microenvironment." (PMID 26318044, 2015). "If on one side tumor cells secrete a plethora of factors such as TGF-β1, PDGF, VEGF, IL-6, FGF-2, IFN-γ, TNF, MMPs involved in fibroblast activation, on the other side CAFs produce the same molecules that in turn affect tumor aggressiveness." (PMID 25474039, 2015). "Further examination of chemokine expression revealed an enrichment of CXCL11, FGF2, IGF-1 and Shh in CD11b+Gr1+ cells isolated from spleen of LLC tumor bearing transgenic mice that lack TGFβRII only on myeloid cells (LysM+)." (PMID 25629162, 2015). "Medulloblastoma cell lines are most sensitive to exogenous HGF (4 out of 5 cell lines), FGF-2 (3 out of 5 cell lines) and EGF (3 out of 5 cell lines) resulting in increased tumor cell growth." (PMID 26496080, 2015). "In tumor cells, the interaction between FGFR2, the progesterone receptor and STAT5 in the nucleus after FGF2 and medroxyprogesterone acetate (MPA) treatment has been associated with increased gene transcription and cell proliferation." (PMID 25970615, 2015). "In the present study, we investigated the role of FGF2, in the regulation of proliferation and survival of GBM tumor cells." (PMID 26056081, 2015). "Studies suggested that FGF2 also exerts anti-apoptotic function through up-regulating anti-apoptotic genes BCL-2 and BCL-XL, making tumor cells resistant to chemotherapy." (PMID 26056081, 2015). "MCs are recruited and activated via several factors secreted by tumour cells, such as the C-Kit receptor or stem cells factor, VEGF, FGF-2, and TP." (PMID 24995015, 2014). "Importantly, FGF2-induced phosphorylation of ERK1/2 within tumor organoids growing in a three-dimensional matrix that recapitulates the pulmonary microenvironment could be effectively blocked using two different pharmacological inhibitors of FGFR kinase activity." (PMID 24618085, 2014). "This downregulation promoted tumor growth and progression through reduced post-transcriptional repression of FGF-2 and its receptor FGFR1, which act on both stromal and tumor cells to enhance cancer cell survival, proliferation, and migration." (PMID 24598126, 2014). "By the way, tryptase can also participate to the neovascular growth by activating latent MMPs, which, in turn, promote tumor invasiveness and release of angiogenic factors (VEGF or FGF-2) from their matrix-bound state." (PMID 25295247, 2014). "FGFs are composed of 22 members that bind and activate the four FGF receptor family members (FGFR1-4); these ligands include the basic FGF (bFGF and FGF2),which plays important role in NSCLC tumor proliferation and angiogenesis." (PMID 24744457, 2014). "Tumor angiogenesis is regulated by a balance of stimulators (e.g., VEGF-A, hepatocyte growth factor, and FGF-2) and inhibitors (e.g., endostatin and vasohibin)." (PMID 25437864, 2014). "The silencing of either FGFR1 or FGF2 arrests tumor growth, suggesting the presence of the FGFR1–FGF2 autocrine loop in the subset of human subcutaneous carcinomas." (PMID 23900974, 2013).
tumor (continued). "As such, HRS cells that harbor the FGF2+/SDC1+ immunophenotype and express both MMP9 and TGFβ1 are the cells most likely to be shed from the tumor microenvironment." (PMID 23988031, 2013). "In human non-small-cell lung carcinomas (NSCLC), FGF2, FGF9, and their respective receptors, were also reported to mediate autocrine signaling which drives tumor resistance to specific kinase targeted therapy." (PMID 23900974, 2013). "TrkA expression inhibits tumor growth and down regulates the angiogenic factors VEGF and FGF-2 in SH-SY5Y cells whereas TrkB transfectants and parental SH-SY5Y cells induced endothelial cell proliferation and migration." (PMID 21876694, 2012). "To evaluate the effect of MSI1-KD on tumor cell colony formation in vitro, we performed methylcellulose gel colony-forming assays in the presence of EGF and FGF2." (PMID 22428049, 2012). "Melanomas were found to express high levels of FGF2 and FGFR1, and inhibition of expression of either of these molecules resulted in inhibition of tumour cell growth and progression, similar to that observed in mouse E-cadherin−/− ES cells and hES cells." (PMID 21197469, 2011). "PG500 series compounds are believed to interfere with two important processes in tumor development, namely angiogenesis via inhibition of VEGF, FGF-1, and FGF-2, and metastasis via inhibition of heparanase activity." (PMID 23908791, 2011). "Some studies have shown that FGF-2 and hypoxia up-regulate PDGFR in the tumor vasculature, but the mechanism by which PDGFRβ is up-regulated by tumor cells needs further investigations." (PMID 27713269, 2010). "Ligands for receptors present on tumor cells or tumor endothelium (e.g. EGF, FGF-2, VEGF) were coupled to PEG-coated virions to specifically target the vector to tumors." (PMID 21994711, 2010). "Tumor derived MCP-1 and CCL5 induce macrophages to secrete angiogenic factors, such as IL-8, VEGF, MMP-9, FGF-2, tumor necrosis factor alfa (TNF-α) and PDGF." (PMID 24281035, 2010). "Similar effects were obtained by neutralizing anti-PDGFR antibodies and results were explained by suppression of FGF-2 and FGF-7, and supported by decreased proliferation of tumor cells and inhibition of angiogenesis." (PMID 27713269, 2010). "Through an interaction with fibroblast growth factor-2 (FGF-2) and vascular endothelial growth factor (VEGF), fibrinogen promotes angiogenesis and tumour cell growth." (PMID 20160724, 2010). "Our analysis of differential expression between adjacent stroma and tumor epithelia showed that the cytokines, CCL5 and CXCL 13, and the growth factors, IGF-1 and FGF-2, were upregulated in stromal cells." (PMID 20426842, 2010). "These tumour stimulatory factors include vascular endothelial growth factor (VEGF-A) and fibroblast growth factor 2 (FGF2)." (PMID 20092633, 2010). "However, FGFR2 signaling in the tumor setting, where FGF2 and FGF7 are likely available from the surrounding microenvironment, may establish a paracrine pathway leading to continued cancer cell survival, growth and maintenance of transformation in the presence of EGFR targeted therapies." (PMID 21152424, 2010). "We focused in those genes that were significantly differently methylated in the basal-like tumor subtype (HOXA9, SOX1, VAMP8, and TNFRS10D) and those that were significantly hypermethylated in the luminal B tumors (NPY, RASSF1, HS3ST2, DBC1, FGF2, CD40." (PMID 20920229, 2010). "Suppression of bFGF, also known as FGF2, is correlated with reduced vascularization and tumor growth." (PMID 19228418, 2009). "Fibroblast growth factor-2 (FGF2) is a heparin-binding angiogenic growth factor involved in various physiopathological processes, including tumor neovascularization." (PMID 22454596, 2009). "Here we investigate the sub-cellular distribution of syndecan-1, FGF-2, FGFR-1 and heparanase in malignant mesenchymal tumor cells, and explore the possibility of their coordinated translocation to the nucleus." (PMID 19802384, 2009).